Y_RNA (Y RNA )
Gene: Miscellaneous RNA gene on chromosome 2 (159,536,244 to 159,536,346, reverse strand). Ensembl gene ENSG00000207117.
Homologues: Orthologues: chimpanzee Y_RNA (99% identical), macaque Y_RNA (89% identical). Paralogues in human: Y_RNA (86% identical), Y_RNA (85% identical), RNY3 (84% identical), Y_RNA (84% identical), RNY3P1 (83% identical), RNY3P14 (83% identical), Y_RNA (83% identical), Y_RNA (82% identical), RNY3P11 (81% identical), RNY3P5 (81% identical), Y_RNA (81% identical), RNY3P7 (80% identical), and 92 more.